TSPY8 (testis specific protein Y-linked 8)
Description:
May be involved in sperm differentiation and proliferation.
Tractability: PROTAC: ubiquitination databases record sites on it.
Gene: Protein-coding gene on chromosome Y (9,357,797 to 9,360,599, forward strand). Ensembl gene ENSG00000229549.
Subcellular location: Cytoplasm; Nucleus
Subcellular location (Human Protein Atlas): Cytosol
Gene Ontology:
Biological process: nucleosome assembly
Cellular component: chromatin; cytoplasm; nucleus
Homologues: Orthologues: macaque TSPY2 (71% identical), zebrafish tspy (28% identical), Drosophila melanogaster Set (23% identical), Caenorhabditis elegans spr-2 (19% identical), Drosophila melanogaster Nap1 (15% identical), Caenorhabditis elegans nap-1 (14% identical), Drosophila melanogaster CG3708 (12% identical), Drosophila melanogaster mil (12% identical), zebrafish nap1l4a (12% identical). Paralogues in human: TSPY10 (99% identical), TSPY3 (99% identical), TSPY4 (99% identical), TSPY9 (99% identical), TSPY1 (99% identical), TSPY2 (99% identical), TSPYL1 (34% identical), TSPYL4 (32% identical), TSPYL5 (31% identical), TSPYL2 (31% identical), TSPYL6 (29% identical), SET (26% identical), and 6 more.
Diseases named in the same sentence as TSPY8 in open-access papers:
TSPY8 is named in the same sentence as 1 disease in open-access papers, as found by Europe PMC text mining. Sharing a sentence is not in itself a finding about the gene and the disease.
TSPY8 shares sentences with these, for which no sentence is quoted: Azoospermia (1 paper).